ALK (ALK receptor tyrosine kinase)
Diseases named in the same sentence as ALK in open-access papers (continued):
Sharing a sentence is not in itself a finding about the gene and the disease.
lymphoma (continued). "Anaplastic lymphoma kinase (ALK) gene rearrangement testing was performed in patients with adenocarcinoma who were EGFR negative; BRAF was performed in patients with melanoma, and C-MYC mutations in patients with lymphoma." (PMID 31429741, 2019). "Our results strongly suggest that combining low doses of ALK inhibitors with IGF-IR inhibitors might represent an effective strategy to successfully eradicate this aggressive lymphoma." (PMID 31340850, 2019). "This drug sensitivity is also detected in other cancer types such as lymphoma cells treated with an ALK kinase inhibitor that became dependent on it, suggesting that intermittent dosing may prolong control of ALK+ tumors." (PMID 34322663, 2019). "Vaccination with ALK DNA led to protection against lymphoma growth in a murine model." (PMID 29642597, 2018). "The 2016 revised World Health Organization (WHO) lymphoma classification recognizes four different entities: systemic ALK-positive ALCL (ALK+ ALCL), systemic ALK-negative ALCL (ALK− ALCL), primary cutaneous ALCL (pC-ALCL), and the provisional entity breast implant-associated ALCL (BI-ALCL)." (PMID 29617304, 2018). "Taken together, these results show that while a G0/G1 cell cycle defect was associated with reduced JunB expression in both cHL and ALK+ ALCL cell lines, the molecular basis for this defect may differ between these lymphomas." (PMID 30375407, 2018). "This study showed the potential of a vaccination against ALK in preventing lymphoma growth in vivo." (PMID 29642597, 2018). "This combination enhanced the survival of mice challenged with ALK-positive lymphomas." (PMID 29495603, 2018). "However, the combination of chemotherapy (a single dose of doxorubicin) with following ALK vaccination significantly enhanced the survival of mice challenged intravenously with 1 × 106 ALK-positive lymphoma cells before therapy." (PMID 29642597, 2018). "The highly aggressive nature of this lymphoma and the relative paucity of molecular data available highlight the need for deeper insights into the molecular pathogenesis of ALK-positive large B-cell lymphomas to identify new and effective alternative treatments." (PMID 28665943, 2017). "ALK-positive ALCL account for 10% to 15% of pediatric lymphoma." (PMID 29186933, 2017). "Although the current World Health Organization classification of lymphomas places ALK(+) and ALK(−) ALCL in the same category, more recent studies suggest that these two types of lymphomas, as well as cutaneous ALCL, might correspond to different entities." (PMID 28331184, 2017). "Simultaneously, ALK rearrangement positive lymphoma cells also expressed sweyjawbu RNA." (PMID 27974674, 2017). "In this framework, our group is interested in understanding the role of autophagy in ALK-positive lymphoma therapy and how the autophagy process could be exploited to improve patients’ treatment." (PMID 29186933, 2017). "Indeed, using our conditional NPM/ALK lymphoma transgenic mouse model, we observed that ALK works alongside HIF1α to boost VEGF (Vascular endothelial growth factor) expression by down-regulating miR-16, an inhibitor of VEGF mRNA." (PMID 28771164, 2017). "Thus, it is possible that stronger immune responses to ALK in NSCLC patients will be associated with improved outcomes, as previously shown for ALK-positive lymphoma patients." (PMID 29190913, 2017). "The assay also could be complementary to FISH and IHC, which might further improve the accuracy and convenience of diagnosis and treatment of ALK rearrangement-positive lymphomas, or even other lymphomas of unknown origin with rare ALK-positive condition." (PMID 27974674, 2017). "First, STAT3 is required for ALK-mediated tumorigenesis in lymphoma." (PMID 29035291, 2017). "Moreover, combining measurements of sweyjawbu expression and the ratio of the 5’ and 3’ portions of the ALK transcript provided even more accurate identification of ALK rearrangement-positive lymphomas." (PMID 27974674, 2017).
lymphoma (continued). "In contrast to ALK-rearranged lymphomas, the frequency and clinical significance of spontaneous ALK immune responses in patients with ALK-rearranged NSCLCs are largely unknown." (PMID 29190913, 2017). "The potential therapeutic benefit of an anti-ALK immune response has been demonstrated in a mouse model of ALK-positive ALCL, in which a DNA-based ALK vaccine was shown to generate ALK-specific cytotoxic T-cell responses and protect mice from developing lymphoma." (PMID 29190913, 2017). "Primary small intestinal ALK positive anaplastic large cell lymphoma is rare." (PMID 27612448, 2016). "Several studies have identified the regulatory roles of ALK in lymphoma and immune systems." (PMID 27598116, 2016). "Moreover, diagnosis of intestinal ALCL should be made after exclusion of other lymphomas which show similar cell morphology and/or ALK positive staining." (PMID 27612448, 2016). "To support this view, we previously showed that ALK controls in vivo liver metastasis formation in NSCLC xenografts in immunocompromised mice and that the ALK oncogene directly regulates morphology, migration and cytoskeleton organization in ALK-rearranged lymphoma." (PMID 27119231, 2016). "Crizotinib has been shown to have in vitro activity against ALK-positive lymphomas." (PMID 27301488, 2016). "We found that ALCL ALK−, in contrast to ALCL ALK+, lymphomas display high miR-155 expression." (PMID 25820993, 2015). "The short survival of our patient may reflect a propensity toward aggressive behavior in lymphomas that express this ALK fusion." (PMID 26187744, 2015). "PD-L1 expression on some tumors may result from oncogenic pathways such as PI3 kinase signalling in gliobastomas in association with PTEN deletion, ALK and STAT3 signalling in lymphomas or mutant EGFR activity in lung tumors." (PMID 25844720, 2015). "It has been reported that ALK induces GLI1 mRNA expression via PI3/Akt in a lymphoma cell line." (PMID 24163262, 2013). "Recently, studies have proposed that proteins such as aberrant fusion protein (NPM-ALK), JAK-STAT, and PI3K/STAT may be a potential target in ALK-positive lymphomas." (PMID 23840974, 2013). "In a final step, we asked whether neoplastic MC in SM express ALK or other lymphoma-related antigens in serial BM sections." (PMID 21297223, 2010). "Based on their morphology, histology, phenotypic properties, and on transfer experiments, MC neoplasms and ALK+ lymphomas could clearly be distinguished in these mice." (PMID 21297223, 2010). "In a second step, we asked whether tumor-specific lymphoma stem cells in established ALK+ lymphomas can give rise to MC neoplasms in secondary recipients." (PMID 21297223, 2010). "The latest WHO classification of lymphomas recognizes ALK-DLBCL as a separate entity." (PMID 19250532, 2009). "In addition, ALK expression in this disease is linked to STAT3 phosphorylation and, hence, STAT3 may represent one of the molecular targets for this lymphoma." (PMID 40869163, 2025). "Using markers of ALK- ALCL we compared the GFP-sorted Donor 4 replicates with the high-grade T cell lymphomas to see if any of the Donor 4 replicates might model HIV-driven lymphoma." (PMID 40627772, 2025). "Other lymphomas with plasmablastic morphology that may aberrantly express T-cell markers include plasmablastic lymphoma and ALK-positive large B-cell lymphoma, which are typically EBV-positive and ALK-positive, respectively; however, our case was negative for both markers." (PMID 39776705, 2024). "Until recently, pcALCL has been considered an ALK-negative lymphoma, although pcALCL may also be ALK-positive; this is a rare phenomenon which occurs practically only in the paediatric population and is associated with progression to the secondary systemic involvement." (PMID 38337516, 2024).
lymphoma (continued). "Moreover, there are numerous reports of ALK inhibitor activity in multiple solid and hematologic tumors (e.g., histiocytosis, leiomyosarcoma, lymphoma, myeloma, and colorectal, neuroendocrine, ovarian, pancreatic, renal, and thyroid cancer) bearing ALK fusions/rearrangements." (PMID 37773318, 2023). "The antigenicity of ALK associated proteins has been well established in human lymphomas, where T and B cells have been found to be immunoreactive for ALK associated proteins by examining CD8 + CTLs, CD4 + helper T lymphocytes directed against ALK epitopes, and ALK associated antibodies." (PMID 36591504, 2022). "Therefore, we can hypothesize that downregulation of CD45 is needed to downregulate TCR signaling in ALK+ ALCL to protect lymphoma cells from apoptosis induced by TCR over-signaling." (PMID 36698412, 2022). "In ALK+ ALCL, the JAK/STAT pathway is a critical downstream mediator of ALK oncogenic signaling sustaining the neoplastic phenotype and contributing to the survival of lymphoma cells; therefore, we investigated whether oncogenic ALK affected CD45 expression and activity." (PMID 36698412, 2022). "Interestingly, further studies found that anti ALK CTLs could effectively inhibit the growth of ALK positive lymphoma cells." (PMID 36591504, 2022). "Finally, the autophagic degradation of anti-apoptotic proteins, such as Fap-1, which is an inhibitor of Fas-mediated apoptosis (as described in BJAB lymphoma cells), could account for cell death and its occurrence in ALK+ ALCL should be investigated." (PMID 34685497, 2021). "Besides, ALK correlated positively with PD-L1 expression in lymphoma." (PMID 34088360, 2021). "Thus, understanding the role of autophagy in the immunological features of NPM-ALK lymphoma cells is an important research field, holding the promise that autophagy manipulation could improve future ALK+ ALCL immune therapies." (PMID 34685497, 2021). "Thus, ALK+ lymphomas may express an ALK fusion protein involved in cancer cell survival, or the Cbp/PAG adaptor protein and the Lyn kinase signalosome that recruits other transcription factors and signaling enzymes." (PMID 32230887, 2020). "Furthermore, we used this same approach to investigate whether stable c-Jun or JunB knock-down results in a similar phenotype in another CD30-positive lymphoma, ALK+ ALCL." (PMID 30375407, 2018). "Interestingly, recent preclinical studies indicate that ALK fulfills the major requirements for an ideal OA for lymphoma vaccination and that a vaccine against ALK can induce a strong specific immune response able to impair the growth of ALK-rearranged lung tumors." (PMID 28763018, 2017). "In addition, it is unknown whether the presence of the ALK oncogene has an impact on DNA methylation in ALK+ compared to ALK− lymphomas." (PMID 27705804, 2016). "Given that ALK+ ALCL tumour cells exhibit high levels of apoptosis and the observed correlation between GzB expression and apoptosis rate in nasal-type NK/T lymphomas and prostate cancer cell lines, we decided to investigate whether GzB expression might sensitize ALK+ ALCL cells to apoptosis." (PMID 25168906, 2014). "The intracellular anaplastic lymphoma kinase (ALK) fragment shows striking homology with members of the insulin receptor family and was initially identified as an oncogenic fusion protein resulting from a translocation in lymphoma and more recently in a range of cancers." (PMID 23267434, 2012). "Unlike classical active-site inhibitors such as mycophenolic acid (MPA), Comp-10 decreases IMPDH1/2 protein levels, blocks filament (rod/ring) formation, and inhibits the growth of ALK and BTK inhibitor-resistant lymphoma cells." (PMID 41154443, 2025).
lymphoma (continued). "All EBV-associated malignancies were anticipated to be PDL1 positive in PCNSL, peripheral T-cell lymphoma, ALK-positive ALCL, extranodal NK/T-cell lymphoma of the nasal type, cutaneous T-cell lymphoma, and adult T-cell leukemia/lymphoma." (PMID 40710189, 2025). "ALK-positive ALCL is a lymphoma with a T-cell/null phenotype, characterized by NPM/ALK fusion and usually following a good prognosis." (PMID 40869163, 2025). "Comp-10 represents a promising therapeutic strategy for ALK-driven and BTK inhibitor-resistant lymphomas and potentially other tyrosine kinase-driven malignancies." (PMID 41154443, 2025). "Short-term systemic pharmacological inhibition of HDACs using the HDACi Entinostat in a premalignant ALCL mouse model postponed or even abolished lymphoma development, despite high expression of the NPM::ALK fusion oncogene." (PMID 40175628, 2025). "The largest prospective study, conducted by the Nordic Lymphoma Group (NGL-T-01), enrolled 115 patients with nodal PTCL (excluding ALK-positive ALCL), of whom 70% underwent auto-SCT." (PMID 40839148, 2025). "The fusion of the anaplastic lymphoma kinase gene, ALK, to the nucleolar protein gene, NPM1 was identified in 1994 in specific lymphoma subtypes." (PMID 38347643, 2024). "In summary, while CD30 expression is a shared feature among these lymphomas, the diagnosis of ALCL is supported by its unique cellular morphology, the potential presence of ALK expression, and its distinct clinical presentation." (PMID 39610919, 2024). "In view of the importance of Myc in regulating the CSL immunophenotype in ALK+ALCL, we hope to gain insights into how cancer stemness is regulated in these lymphoma cells." (PMID 37762644, 2023). "ALK+ ALCL is among the most prevalent subtypes of T-cell lymphoma, accounting for 10-30% of all lymphomas in adolescent." (PMID 38143760, 2023). "In a few publications using immunohistochemistry applied to cohorts of ALK+ALCL patient samples, high Myc expression in lymphoma cells was found to significantly correlate with a shorter overall survival." (PMID 37762644, 2023). "Murine tumors displayed the phenotypic diversity observed in ALK+ ALCL patients, including CD4+ and CD8+ lymphomas." (PMID 35246138, 2022). "This lymphoma, ALK-negative ALCL and ALK-positive large B-cell lymphoma were formally recognized in the 2008 WHO classification." (PMID 35011737, 2022). "Moreover, such potential NPM-ALK containing autophagosomes, once released from dying ALK lymphoma cells, could be captured by dendritic cells in the tumor microenvironment and their content could therefore be redirected to MHC class I complex for processing and cross-presentation in other cancers." (PMID 34685497, 2021). "Lymphoma cells show strong and uniform CD30 expression and aberrant expression of anaplastic lymphoma kinase (ALK) protein due to translocations involving the ALK gene at the 2p23 locus." (PMID 33412518, 2021). "Lymphomas with the lowest SNV/Indel numbers were in the order of ALCL, ALK-positive (ALCL, ALK+) (median: 14), follicular T-cell lymphoma (median: 14), and nodal peripheral T-cell lymphoma with TFH phenotype (PTCL TFH) (median: 14.5)." (PMID 34461835, 2021). "At interim scanning, residual lymphoma-related activity was measurable in 32 ALK-negative PTCL and nine ALK-positive ALCL." (PMID 34523055, 2021). "Immunohistochemistry for p63 is not specific for a TP63 rearrangement but it is a useful screening test to select cases of ALK- ALCL for TP63 FISH, particularly in cases with >30% positive lymphoma cells." (PMID 34572893, 2021).
lymphoma (continued). "Brentiximab vedotin is effective in treating relapsed or refractory cHL and ALK+ ALCL, and shown to be promising as a frontline treatment for these lymphomas in combination with chemotherapy." (PMID 33413671, 2021). "NPM-ALK, CLTC-ALK, and SQSTM1-ALK translocations lead to ALK and STAT3 phosphorylation with downstream oncogenic activation of the transcription factor STAT3, which enhances lymphoma cell proliferation and growth." (PMID 34283060, 2021). "On the basis of our previous study, the aberrant expression of Sox2 in these lymphoma cells is attributed to the constitutive activation of the NPM-ALK/STAT3 axis, and inhibition of either ALK or STAT3 led to a substantial decrease in Sox2 expression." (PMID 34287231, 2021). "Among others, comboFM predicted a particularly high level of synergy for the combination between anaplastic lymphoma kinase (ALK) inhibitor crizotinib and proteasome inhibitor bortezomib in lymphoma cell line SR." (PMID 33262326, 2020). "MAX expression in ALK-positive ALCL patients was significantly lower than in PTCL-NOS in the GSE65823 dataset, whereas MYC mRNA levels were comparable among these lymphomas." (PMID 32587329, 2020). "Our comboFM method predicted combination partners to extensively explored ALK and EGFR inhibitors for lymphoma, which we were able to also validate in the experimental setting." (PMID 33262326, 2020). "The ALK-NPM fusion appears to allow expression and activity of ALK in lymphatic tissues which contributes to the development of lymphomas." (PMID 32283832, 2020). "This indicates that while the role of JunB in promoting proliferation is largely similar in cHL and ALK+ ALCL cell lines, the importance of c-Jun in regulating proliferation differs between these two CD30–positive lymphomas." (PMID 30375407, 2018). "More than 60% of children and adolescents with ALK-positive ALCL present with B-symptoms, suggesting an unspecific stimulation of the immune system by the lymphoma." (PMID 29642597, 2018). "In order to determine any minimal involvement of lymphoma in the first lymph node biopsy and for bone marrow staging, immunostaining was performed for CD30 and ALK protein in both samples." (PMID 28490385, 2017). "Because NPM-ALK is the most widely expressed ALK chimeric protein and because all established ALK+ T-cell ALCL cell lines harbor NPM-ALK, in this paper we will refer to this lymphoma as NPM-ALK+ ALCL." (PMID 25026277, 2014). "This transcription factor also promotes the expression of CD30 and the cytotoxic protein, Granzyme B, in ALK+ ALCL, which are phenotypic characteristics of this lymphoma." (PMID 22681779, 2012). "Hsp90 is vitally important for the proliferation and survival of ALK+ ALCL cell lines, and is required for the expression and/or activation of important signalling proteins in this lymphoma." (PMID 22681779, 2012). "These lymphomas express the CD30 (Ki-1) surface antigen, but the morphologic identification of ALK+ ALCL can be challenging, as the cytologic features of the tumor cells can be highly variable from case to case." (PMID 22852078, 2012). "These include anaplastic lymphoma kinase (ALK)-positive large B-cell lymphoma (ALK+ LBCL), and the so-called grey zone lymphomas or lymphomas with intermediate features and the posttransplant lymphoproliferative disorders." (PMID 22611401, 2012). "Only one case received immunotherapy with rituximab despite the CD20-negative nature of ALK-DLBCL; this patient died of lymphoma 6 months after diagnosis." (PMID 19250532, 2009). "IgG4 was positive in some of the IgG-positive plasma cells, and anaplastic lymphoma kinase (ALK) staining was negative, effectively ruling out an ALK-positive inflammatory myofibroblastic tumor, ALK-positive histiocytosis, and ALK-positive lymphoma." (PMID 40429964, 2025). "Unlike PBL and EC-PEL, ALK-positive LBCL is an aggressive lymphoma occurring in immunocompetent individuals." (PMID 40869163, 2025).